ACTA2 (actin alpha 2, smooth muscle)
Diseases named in the same sentence as ACTA2 in open-access papers (continued):
Sharing a sentence is not in itself a finding about the gene and the disease.
gastric cancer (9 papers, 2022 to 2025). A primary or metastatic malignant neoplasm involving the stomach. "Bone marrow transplantation experiments in a mouse model of gastric cancer showed that 20% of ACTA2+ CAFs were recruited from the bone marrow." (PMID 40745121, 2025). "CAFs, marked by ACTA2 expression, were notably more abundant in diffuse and mixed-type gastric cancers." (PMID 41584584, 2025). "Recent studies have shown that gastric cancer patients with high expression of ACTA2 have poor prognosis and poor response to immunotherapy." (PMID 38693916, 2024). "ACTA2 was included in a 32-gene signature that defined four molecular and prognostic subgroups of gastric cancer." (PMID 37296997, 2023). "Dual immunohistochemistry staining showed high expression of CD8 and ACTA2 in gastric cancer tissue." (PMID 37180146, 2023). "To validate the relationship of CAFs and immune infiltration, we used double-staining immunohistochemistry to detect the CAF marker ACTA2 and the CD8+ T cell marker CD8.The result showed that the expression of ACTA2 was upregulated in the gastric cancer accompanied with the high expression of CD8." (PMID 37180146, 2023). "qRT-PCR analysis revealed that both ACTA2 and VIM were significantly upregulated in gastric cancer tissues compared to adjacent normal tissues (p < 0.01)." (PMID 40677704, 2025). "C11_VWF were characterized by co‐expressing marker genes of fibroblasts (COL1A1, FAP, VIM, ACTA2) and endothelial cells (VWF, PECAM1, CLDN5, FLT1, RAMP2), which resembled a subgroup of cells undergoing an EMT transition in gastric cancer." (PMID 38115703, 2023). "Although STF1 and STF3 clusters exhibited upregulation of FAP, ACTA2, and TAGLN, the STF2 cluster exhibited upregulation of only CSPG4, further indicative of distinct CAF sublineages in gastric cancer." (PMID 34642171, 2022).
lung adenocarcinoma (9 papers, 2016 to 2023). A carcinoma that arises from the lung and is characterized by the presence of malignant glandular epithelial cells. "Overexpression of ACTA2 had an increased risk of distant metastasis and worse survival for lung adenocarcinoma patients." (PMID 33384961, 2020). "ACTA2 has been reported to promote invasion and metastasis in lung adenocarcinoma by regulating c-MET and FAK expression." (PMID 36768307, 2023). "Other in vitro experiments showed that migration, invasion, clonogenicity, and transendothelial penetration of lung adenocarcinoma cells were significantly impaired by downregulation of ACTA2." (PMID 34179721, 2021). "ACTA2 silencing significantly increases E-cadherin expression but decreases vimentin expression in lung adenocarcinoma cells." (PMID 28881584, 2017). "Lung adenocarcinomas with high smooth muscle actin gene ACTA2 expression showed significantly enhanced distant metastasis and unfavorable prognosis." (PMID 27018053, 2016). "Down-regulation of ACTA2 dramatically decreased lung adenocarcinoma cell movement and invasion." (PMID 37274283, 2023). "In addition, in patients with lung adenocarcinomas and high expression levels of ACTA2 in tumor cells, distant metastasis and unfavorable prognosis are increased substantially." (PMID 34179721, 2021). "We detected a relationship between C1q and TGF-β1 as well as other mesenchymal markers (ACTA2, COL1A1, and CTGF) in lung adenocarcinoma using the online tool TIMER2.0." (PMID 35078421, 2022). "ACTA2 upregulation in lung adenocarcinoma cells was also connected to expression of c-MET and focal adhesion kinase (FAK), whereas ACTA2 targeting by small interfering RNAs (siRNAs) and short hairpin RNAs (shRNAs) resulted in loss of mesenchymal characteristics." (PMID 27018053, 2016).
Marfan syndrome (9 papers, 2012 to 2025). A disorder of the connective tissue. "In total, 176 pregnancies in 170 women (mean age 32 years, 56% primigravida) with HTAD were included: 122 with Marfan syndrome, 14 with Loeys–Dietz syndrome, 10 with ACTA2 variants, and 30 with other diagnoses." (PMID 40576452, 2025). "Six patients suffered from connective tissue disease, namely Marfan syndrome, Loeyz-Dietz syndrome, alpha smooth muscle actin (ACTA2) mutation or suspected genetic aortic syndrome (GAS)." (PMID 34934131, 2021). "Since little data on pregnancies in ACTA2 mutation carriers are available, we recommend management in pregnant women as for pregnant women with Marfan syndrome." (PMID 31752940, 2019). "Patients with Loeys-Dietz syndrome (LDS, n = 12), Marfan syndrome (MFS, n = 11), and familial thoracic aortic aneurysm 6 (FTAA6, n = 9), i.e., actin alpha 2 (ACTA2) pathogenic variants, were recruited." (PMID 36606286, 2022). "TAA is associated with known connective tissue disorders, for example, Marfan syndrome (OMIM: 154700), and genetic causes of nonsyndromic (familial or isolated) cases of TAA, including mutations in the genes ACTA2, MYH11, TGFBR2, have been established." (PMID 22970404, 2012). "Interestingly, both Marfan syndrome (caused by FBN1 mutations) and familial TAA caused by ACTA2 mutations are associated with aortic valve malformation." (PMID 22970404, 2012). "Among them, 51 patients had genetically confirmed HTAD (Marfan syndrome (FBN1), Loeys-Dietz syndrome (TGFBR1, TGFBR2, SMAD3, TGFB2), vascular Ehlers-Danlos syndrome (COLSA1), and non-syndromic HTAD (ACTA2, MYH11, MYLK))." (PMID 41310758, 2025). "The best characterized genes include FBN1 [Marfan syndrome (MFS)], TGFBR1 and TGFBR2 [Loeys-Dietz syndrome (LDS)], SMAD3 [aneurysm-osteoarthritis syndrome (AOS)], and ACTA2 [Aortic and Cerebral Aneurysm (ACA)]." (PMID 36312254, 2022).
melanoma (9 papers, 2017 to 2024). A malignant, usually aggressive tumor composed of atypical, neoplastic melanocytes. "In the mouse melanoma xenograft model, similar expression trendy of ACTA2 and KDR genes were observed to that in the clinical dataset." (PMID 34179721, 2021). "We also investigated the correlation of the seven prognostic-associated TBCs between MMP-related genes (MMP2, MMP9, MMP7, MMP14, BSG, EGFR, MMP1, MMP3) and EMT-associated genes (TWIST1, VIM, CDH2, ACTA2, ZEB1), which also indicated a central role of TBCs in melanoma." (PMID 33194704, 2020). "Interestingly, melanomas with elevated levels of ACTA2 were resistant to ICT." (PMID 37762086, 2023). "Unbiased scRNA-seq analysis of small and large melanoma tumours showed that CAF activation in Atf4Δ/Δ mice was impaired; this was based on the expression levels of Acta2 and Pdgfrb, which are the most commonly used CAF markers." (PMID 35654839, 2022). "Our study revealed that ACTA2 and KDR could be used as responsive markers for PD‐1/PD‐L1 blockade therapy in melanoma." (PMID 34179721, 2021). "Similar to other CAF data, scRNA seq of melanoma and skin cancer CAFs confirms that canonical markers often overlap, but not completely; while Pdpn and Pdgfra colocalize, aSMA/Acta2 may be a different population in melanoma." (PMID 38525245, 2024). "Furthermore, we noticed an increase in DUSP1 (Dual Specificity Phosphatase 1), STK3 (Serine/Threonine Kinase 3), ACTA2 (Actin, alpha 2, smooth muscle, aorta) and IL1A (Interleukin 1α) gene expression levels; however, the role of these genes in melanoma repopulation remains to be addressed." (PMID 31597943, 2019).
diabetes (8 papers, 2014 to 2024). "This study aimed to analyze the correlation between single nucleotide polymorphisms (SNPs) of the actin, aortic smooth muscle (ACTA2) gene and coronary artery stenosis in patients with type 2 diabetes mellitus (T2DM)." (PMID 24669260, 2014). "Gene expression of the myofibroblast marker α-smooth muscle actin (Acta2) and matrix molecules collagen 1 (Col1a1), collagen IV (Col4a3) and fibronectin (Fn1) were all increased 2- to 3- fold in kidneys at week 12 of diabetes." (PMID 38391050, 2024). "There was diabetes-induced upregulation of Acta2 (an indicator of fibrosis), Fn1 (participates in extracellular matrix formation), and Col 4 (main component of the glomerular basement membrane) in renal tissues." (PMID 34149434, 2021). "Venn diagram analysis revealed that seven DEGs (CXCL8, MLXIPL, CREB3L1, EGR1, NOTCH3, ACTA2, and SERPINE1) were associated with both obesity and diabetes-associated pathways, including non-alcoholic fatty liver disease, insulin resistance, thermogenesis, and apelin signaling pathways." (PMID 38570815, 2024). "Furthermore, early diabetes amplified Acta2 gene expression." (PMID 34561469, 2021). "A whole-transcriptome study revealed differentially expressed target genes important in obesity and diabetes-related pathways such as MLXIPL, CREB3L1, EGR1, ACTA2, SERPINE1, NOTCH3, and CXCL8." (PMID 38570815, 2024).
myocardial infarction (8 papers, 2019 to 2024). Gross necrosis of the myocardium, as a result of interruption of the blood supply to the area, as in coronary thrombosis. "On the other hand, following myocardial infarction in adult mice and postnatal day 8 (P8) neonates, there was a robust upregulation of Acta2 expression by fibroblasts 3 days post injury, a feature which was absent in the adult zebrafish after cardiac injury." (PMID 36271843, 2023). "Reactivation of natriuretic peptide A (Nppa) and smooth muscle actin alpha 2 (Acta2) is the golden standard to assess the quality of the myocardial infarction model." (PMID 33244469, 2020). "A recent study of single cell analyses revealed the up-regulation of fibrotic gene profiles: Postn, Acta2, Adam12, Lox, Wisp1, and Ddr2 during cardiac remodeling in response to angiotensin II and after myocardial infarction." (PMID 31417912, 2019). "In addition, CAR3 deficiency dampened the mRNA levels of ECM-related genes Col1A1, Col3A1, Postn and Acta2 after myocardial infarction." (PMID 38481818, 2024). "Moreover, chronic administration of haloperidol to mice for ten days after acute myocardial infarction resulted in a reduced scar size and Acta2-positive myofibroblasts." (PMID 39200372, 2024).
pulmonary hypertension (8 papers, 2014 to 2024). Increased pressure within the pulmonary circulation due to lung or heart disorder. "CNN1 and TAGLN with ACTA2 were implicated in Smooth Muscle Cell Dysfunction in Pulmonary Hypertension (q = 2.622x10-3)." (PMID 39480826, 2024). "FOXF1 with ACTA2 was associated with Intestinal Malrotation (HP:0002566, q = 1.351x10-2) and Pulmonary Hypertension (HP:0002092, q = 2.318x10-2)." (PMID 39480826, 2024). "Other mutations in Acta2 behaved as a multi-systemic syndrome with cerebral vascular disease and pulmonary hypertension." (PMID 28806738, 2017). "There is increased expression of α-smooth muscle actin Acta2, indicating greater muscularization of pulmonary vessels and possible pulmonary hypertension." (PMID 24722050, 2014). "In addition, the increased expression of ACTA2 in the lungs indicates vascular remodeling in the pulmonary circulation that favors pulmonary hypertension as well." (PMID 39452062, 2024). "Greater expression of Acta2 could also be due to endothelium-to-mesenchyme transition that is found to accompany vascular remodeling in pulmonary hypertension." (PMID 24722050, 2014). "We have recently demonstrated that pioglitazone attenuates TGF-β1 induced pulmonary arterial hypertension and remodeling in the TGF-β1 overexpressing mouse, via decreasing TGF-β1, CTGF and α-smooth muscle actin (Acta2) expression in pulmonary arterial SMC." (PMID 31277592, 2019). "Although we could not directly prove whether SHRs* have pulmonary hypertension, increased endothelin-1 and ACTA2 expression predicts an increase in RV afterload and subsequent RVH." (PMID 39452062, 2024).
colon cancer (7 papers, 2020 to 2023). "Similar to our results, conditioned medium from colon cancer cells can enhance SERPINE1 and ACTA2 expression by CAFs." (PMID 33311557, 2021). "Correspondingly, we found that colonic cancer cells responded to IL-4 and IL-13 stimulation with upregulation of CLDN2, significantly so in case of IL-4, while ACTA2 and TJP1 tended to be rather downregulated, significantly so in case of Caco-2 stimulation with IL-4." (PMID 32512917, 2020). "Thus, we examined the effect of exogenous TGFβ treatment on TAGLN expression, as well as on the expression of a number of TGFβ-responsive genes (ACTA2, and TPM1), in the RKO colon cancer cell model." (PMID 32393769, 2020). "In addition, the Oncomine and GEPIA databases showed that TRPC3 expression is higher in colon cancer tissues compared with normal colon tissues, and was positively correlated with the expression of the CAF genes alpha-smooth muscle (α-SMA/ACTA2) and fibroblast activation protein Alpha." (PMID 35870973, 2022). "In IHC analysis, ACTA2, but not FAP, was strongly detected in smooth muscle cells of colon cancer tumor tissues, indicating the lack of cell specificity in ACTA2 to define CAFs populations in colon cancer." (PMID 37964075, 2023).
heart failure (7 papers, 2018 to 2025). Inability of the heart to pump blood at an adequate rate to meet tissue metabolic requirements. "Despite its location at a considerable distance from the GWAS association, chromatin interactions provide an important level of evidence that ACTA2 is a putative causal gene in the development of heart failure." (PMID 29988018, 2018). "Stress fiber-related genes, such as Acta2 and Tagln were up-regulated in arterial EC during the heart failure phase." (PMID 40772900, 2025). "However, ACTA2 was reported to be upregulated in PBMCs from dogs with heart failure or in children immunized with inactivated influenza vaccine." (PMID 39139572, 2024). "Additionally, the ACTA2 gene is located 220 kb away from the heart failure GWAS locus proximal to the CH25H and LIPA genes on chromosome 10q21." (PMID 29988018, 2018). "Double staining of ACTA2 and PECAM1 (CD31) identified pericyte abnormalities in patients with heart failure." (PMID 37845397, 2023).
arteriopathy (6 papers, 2018 to 2025). "We analyzed the neuroimaging features of all four variant carrying family members and discussed the cerebrovascular abnormalities we found on the background of the current literature on ACTA2 arteriopathies." (PMID 37587538, 2023). "In addition to the known association between Met46, Arg179 and Arg258 substitutions and ACTA2-related arteriopathy, this case illustrates the possibility that Asn117 also plays an important role in α-SMA function within the cerebrovascular smooth muscle cell." (PMID 32093627, 2020).
bladder cancer (6 papers, 2018 to 2025). "ACTA2 was previously found to be associated with the prognosis of bladder cancer." (PMID 33388091, 2021). "All these findings suggested that ACTA2, FLNA, TAGLN and TPM1 were potential diagnostic biomarkers for bladder cancer." (PMID 37274283, 2023). "Similar results were obtained with CAF marker ACTA2 expression, suggesting an activation of fibroblasts in aggressive bladder cancer." (PMID 30744595, 2019). "For these analyses, bladder cancer patients were stratified based on low and high quartiles of ACTA2/IL6 co-expression levels in tumors." (PMID 30744595, 2019). "We also observed that IL6 expression is up-regulated in aggressive bladder cancer tissues, correlates with CAF marker ACTA2 and is associated with a poor prognosis." (PMID 30744595, 2019). "The results showed that the expression levels of ACTA2, CCNB1, CDC20 and VEGFA were associated with the prognosis of patients with bladder cancer." (PMID 30533316, 2018). "The results of the analysis showed that seven genes (VCL, FLNA, THBS1, TAGLN, ACTA2, COL6A2, and CALD1) were significantly correlated (P < 0.05) with the prognosis of bladder cancer patients, and these genes were included in the subsequent in-depth study." (PMID 41181151, 2025). "Next, we performed the survival analysis of these eight genes (ACTA2, CDH1, CCNB1, FLNA, MCM5, MAD2L1, TAGLN and TPM1) in bladder cancer." (PMID 37274283, 2023). "Bioinformatic analyses demonstrated that the expression of ACTA2, FLNA, TAGLN and TPM1 in bladder cancer was markedly downregulated relative to nearby normal tissue." (PMID 37274283, 2023). "In bladder cancer, IL-6 correlated with CAF marker ACTA2 and negatively correlated with tumor purity, suggesting that CAFs were the main source of IL-6 in the TME." (PMID 32637576, 2020). "We analyzed IL6 and ACTA2 expression in the publicly available TCGA and GSE13507 gene expression profiling datasets of human bladder cancer samples." (PMID 30744595, 2019). "Survival analysis revealed that the expression levels of ACTA2, CCNB1, CDC20 and VEGFA were related to the prognosis of patients with bladder cancer." (PMID 30533316, 2018). "Overall, Alterations in the expression of VCL, FLNA, TAGLN, ACTA2, COL6A2, and CALD1 may play important roles in the development of bladder cancer, suggesting their potential value in early detection, molecular subtyping, and targeted therapy." (PMID 41181151, 2025). "Finally, six B-cell marker genes (VCL, FLNA, TAGLN, ACTA2, COL6A2, and CALD1) that were downregulated in bladder cancer were screened using the PPI network, survival curves, ROC curve analysis, and expression validation." (PMID 41181151, 2025). "By survival analysis, we found that their overall survival and disease-free survival curves also showed similarities, such as ACTA2 and TAGLN, FLNA and TPM1, suggesting that these genes have similar functions and are likely to be co-expressed and play a synergistic role in bladder cancer." (PMID 37274283, 2023). "Finally, we observed that IL6 expression is up-regulated in aggressive bladder cancer and correlate with CAF marker ACTA2." (PMID 30744595, 2019).
colorectal cancer (6 papers, 2017 to 2024). A primary or metastatic malignant neoplasm that affects the colon or rectum. "Furthermore, ACTA2 expression is associated with distant metastasis and poor prognosis in human epidermal growth factor receptor-positive breast, bladder, and colorectal cancers." (PMID 37891844, 2023). "To further verify the relationship between TRPC3 and CAFs, we detected the expression of TRPC3 and ACTA2 in clinical specimens of colorectal cancer patients." (PMID 35870973, 2022). "In contrast to CAFs from pancreatic and colorectal carcinomas, where expression of ACTA2 is elevated, ACTA2 expression was very similar in MF and normal fibroblasts after short-term co-culture with MyLa cells." (PMID 33941102, 2021). "Colorectal cancer patients with high ACTA2 expression have a shorter disease-free survival and ACTA2 expression is a significant prognostic factor comparable to lymph node metastasis." (PMID 28881584, 2017). "Finally, in the simulated colorectal tumor data for the eight patients, we demonstrated the robustness of REOs against PTEC variations by analyzing two genes, SFRP1 remarkably under-expressed in colorectal tumor tissues and ACTA2 over-expressed in malignant colorectal tumor stromal cells." (PMID 28427173, 2017). "The result showed that CAFs in colorectal cancer tissues co-expressed TRPC3 and ACTA2." (PMID 35870973, 2022).